TTN (titin)
Diseases named in the same sentence as TTN in open-access papers (continued):
Sharing a sentence is not in itself a finding about the gene and the disease.
hepatocellular carcinoma (8 papers, 2020 to 2024). A malignant tumor that arises from hepatocytes. "In a study on hepatocellular carcinoma, the TTN gene‐related lncRNA TTN‐AS1 was found to regulate the transcriptional activity of relevant genes by targeting miR‐16‐5p and the tumour suppressor gene PTEN, resulting in decreased sensitivity of tumour cells to sorafenib." (PMID 37499109, 2023). "MUC16 and TTN, which are mutated in 11.1% and 20.2% of human hepatocellular carcinomas, were not captured by exome sequencing." (PMID 35557512, 2022).
myocardial infarction (8 papers, 2017 to 2025). Gross necrosis of the myocardium, as a result of interruption of the blood supply to the area, as in coronary thrombosis. "Indeed, recent results demonstrate that titin-based stiffness of cardiomyocytes is increased in the early phases after myocardial infarction, but the underlying mechanisms are not fully understood." (PMID 30584979, 2019). "We propose that variation of the redox state of titin may underlie maladaptive mechanical function of the myocytes after a myocardial infarction." (PMID 30584979, 2019). "We have previously reported that urinary titin can be a biomarker for skeletal muscle atrophy in patients with critical illnesses such as acute stroke, acute myocardial infarction, and diabetes." (PMID 40076646, 2025). "We found the elevated cardiac troponin expression (TNNT2, TNNI3, TTN) in cardiomyocytes across various CHD subtypes, suggesting increased myocardial stress and potential heart attack risk." (PMID 41010342, 2025). "LAVi, indexed left atrial volume; LVEDVi, indexed left ventricular end‐diastolic volume; LVEF, left ventricular ejection fraction; MI, myocardial infarction; RVEF, right ventricular ejection fraction; TTNtv, titin truncating variant." (PMID 37702310, 2024). "An association with the pathogenesis of atherosclerosis has been shown for circulating complement C3, and with acute myocardial infarction for titin and fibrillin-1." (PMID 28273075, 2017). "Additionally, titin is detectable in urine as early as 2 h after the onset of cerebral infarction, and elevated titin levels have been observed in patients with acute myocardial infarction." (PMID 40076646, 2025).
ovarian carcinoma (8 papers, 2020 to 2025). A malignant neoplasm originating from the surface ovarian epithelium. "Further elucidation of the mechanisms underlying attenuated titin expression holds promise for advancing our understanding of ovarian cancer pathogenesis." (PMID 39944242, 2025). "To date, the link between TTN mutation and social, clinical, and genetic factors in ovarian cancer remains unexplored." (PMID 37239452, 2023). "Additionally, few studies have linked TTN mutations to cancer cell activity and prognosis of oncogenic mutations in ovarian cancer." (PMID 37239452, 2023). "Here, we show a significant decrease in titin expression in the tissues and sera from advanced-stage ovarian cancer compared to early-stage patients and healthy controls." (PMID 39944242, 2025). "This study explores the role of titin, a giant muscle protein, in the progression of epithelial ovarian cancer (EOC)." (PMID 39944242, 2025). "The Gene Expression Profiling Interactive Analysis (GEPIA) database was used to examine TTN expression in ovarian cancer tissues." (PMID 39944242, 2025). "A recent study showed that a spontaneous mutation of the titin gene (TTN) represents a tumor mutation burden (TMB) associated with various cancers, including ovarian cancer." (PMID 37239452, 2023). "Saed and colleagues validate the role of titin in epithelial ovarian cancer (EOC)." (PMID 39944242, 2025). "Finally, to determine if the genes that display altered mRNA expression levels in ovarian cancer patient samples (PIK3CA, TTN, RYR2, KMT2C, KRAS, PTEN, and ARID1A) have any clinical value, we checked the effect of their expression on recurrence and survival of patients with ovarian cancer." (PMID 32626534, 2020). "In addition to that, the function of TTN, CSDM3, RYR2, USH2A and SYNE1 has never been established in ovarian cancer." (PMID 32626534, 2020).
Atrophy (7 papers, 2012 to 2022). Any weakening or degeneration, especially through lack of use. "In contrast to titin, shortening of nebulin has been associated with the development of muscle atrophy." (PMID 35642060, 2022). "Any mechanism that increases degradation rates (SRF, ribosomes, and titin degradation rates in our model) will necessarily cause atrophy, and our model confirms this (Section E for detail)." (PMID 34389312, 2021). "For instance, TTN is a structural protein abundant in myofibers whose deficiency was found to be associated with DM perifascicular atrophy (DM-PFA); miR-1 is a muscle specific miRNA that has an important role in muscle development." (PMID 23171592, 2012). "On comparing the diaphragm atrophy and unchanged groups, the levels of urinary titin N-fragment were not higher in the diaphragm atrophy group than those in the unchanged group (147.9 vs. 192.4 pmol/mg in the unchanged vs. atrophy group, p = 0.33)." (PMID 33561946, 2021). "The combination of increased diaphragm thickness and atrophy also did not have a significant difference in terms of the cumulative level of urinary titin N-fragment (147.9 (79.0–257.8) vs. 206.5 (99.3–440.8) pmol/mg Cr in unchanged vs. combination, p = 0.31)." (PMID 33561946, 2021).
Autoimmunity (7 papers, 1992 to 2024). The occurrence of an immune reaction against the organism's own cells or tissues. "These immunological and structural data will allow further studies into the atomic determinants underlying titin-based autoimmunity, improved diagnostics and how to eventually treat titin autoimmunity associated co-morbidities." (PMID 36830985, 2023). "1/5 (20%) had concomitant LGI-1 autoimmunity while the rest were considered as false positive for titin and recoverin." (PMID 38438516, 2024).
cutaneous melanoma (7 papers, 2018 to 2025). A primary melanoma arising from atypical melanocytes in the skin. "TTN, a potential skin cutaneous melanoma related marker, was co-mutated with MUC4 in HCC based on our analysis." (PMID 36081995, 2022). "TTN is the most commonly mutated gene in skin cutaneous melanoma (SKCM)." (PMID 36704353, 2022). "Similarly, TTN was among the most frequently somatically mutated genes in both cohorts regardless of tissue site (brain, LN, or skin), and MUC16 was frequently mutated in both MDACC and Duke MBM, similar to previous reports in primary cutaneous melanomas." (PMID 40457397, 2025). "For example, via modulating TTN expression, the lncRNA TTN‐AS1 speeds up the carcinogenesis and spread of cutaneous melanoma." (PMID 35588441, 2022).
glioblastoma (7 papers, 2019 to 2023). The most malignant astrocytic tumor (WHO grade IV). "The EGFR and TTN mutations were the most frequent mutations in glioblastoma of ArMRS low-risk group." (PMID 37214463, 2023). "On the contrary, the mutation of PTEN, EGFR, TTN, NF1, SPTA1 and RB1, which occurred frequently in glioblastoma, were more frequently in PVT1 higher group." (PMID 37202742, 2023).
channelopathies (6 papers, 2015 to 2023). "Regarding clinically diagnosed channelopathies or SCD cases with no heart alterations identified during autopsy, variants in TTN should be considered as incidental findings not directly associated with any channelopathy." (PMID 26516846, 2015).
congenital muscular dystrophy (6 papers, 2012 to 2024). A muscular dystrophy that is characterized by diminished muscle tone (hypotonia), progressive muscle weakness and degeneration (atrophy), abnormally fixed joints, spinal rigidity, and delays in reaching motor milestones such as sitting or standing unassisted. "Less common disorders, such as titin deficiency causing LGMD2J, and variants of congenital muscular dystrophy such as phenotypes caused by LARGE gene mutations would also benefit from expression of the full length protein." (PMID 22720081, 2012). "Causative variants were found in nine patients with congenital muscular dystrophy in the ACTA1 gene (in one patient), GFPT1 (in one patient), PIGY (in two patients), POMT1 (in one patient), MCU1 (one patient), RYR1 (one patient), and TTN (one patient)." (PMID 37989827, 2024).
diabetic cardiomyopathy (6 papers, 2019 to 2025). Diabetic cardiomyopathy is a disorder of the heart muscle in people with diabetes. "Diabetic cardiomyopathy is also associated with alterations in titin phosphorylation, and common diabetic drugs, such as metformin, have been identified to alter titin phosphorylation, enhancing diastolic compliance." (PMID 40869375, 2025). "The two intronic SNPs in the titin gene (rs2291313 and rs4471922) might indirectly influence the diastolic dysfunction observed in the presence of diabetic cardiomyopathy." (PMID 40650017, 2025). "Therefore, insulin signaling regulates both titin-isoform composition and titin phosphorylation in embryonic cardiomyocytes and could contribute to an altered diastolic function in diabetic cardiomyopathy." (PMID 35135591, 2022).
ischemic heart disease (6 papers, 2013 to 2025). "As mentioned, one ICM patient had a LP variant in TTN, consistent with genetic susceptibility to myocardial dysfunction to which ischemic heart disease further contributed." (PMID 39910139, 2025). "Another interesting observation is that the N2BA TTN isoform normally repressed by RBM20 is upregulated in ischemic heart disease and in dilated cardiomyopathy." (PMID 30948719, 2019). "Changes of titin isoform expression are also known to occur in ischemic heart disease in both humans and rats." (PMID 27233767, 2016). "Chronically ischemic LVs of coronary-artery-disease (CAD) patients with congestive heart failure (HF) had nearly 50% N2BA titin (compared to N2BA+N2B) while approximate 30% N2BA was found in the LVs of control donor patients." (PMID 24367651, 2013).
metabolic syndrome (6 papers, 2021 to 2025). A cluster of metabolic risk factors for CARDIOVASCULAR DISEASES and TYPE 2 DIABETES MELLITUS. "Evidence from a rodent model of the metabolic syndrome and from type I diabetic mice indicates that dysregulation of the sarcomere protein titin is sufficient to induce diastolic dysfunction, even in the absence of cardiac fibrosis." (PMID 34095245, 2021). "Here, we optimized RBM20-ASO dosing in a HFpEF mouse model that closely mimics human disease, characterized by metabolic syndrome and comorbidities, but without primary defects in titin or RBM20." (PMID 41104480, 2025). "TTN/CCDC141 is highly expressed in the heart, suggesting its potential role in biochemical pathways and cardiovascular health, but it has not yet been discussed under the scope of dyslipidemia and atherogenic indexes." (PMID 37372394, 2023).
pancreatic cancer (6 papers, 2020 to 2023). "The TTN gene, which encodes titin protein, a critical element in the construction and function of vertebrates’ striated muscles, is often altered in main pancreatic cancer." (PMID 37313463, 2023). "TTN was also the 4th most commonly mutated gene in pancreatic cancer." (PMID 32033319, 2020).
prostate carcinoma (6 papers, 2015 to 2025). A carcinoma that arises from epithelial cells of the prostate gland.
thyroid cancer (6 papers, 2018 to 2025). "TTN mutations have been shown to be an independent risk factor for thyroid cancer and to predict a poorer prognosis for patients." (PMID 37730847, 2023). "TTN mutation has been correlated with longer progression-free survival and response to immune checkpoint receptor blockade therapy in solid tumors and is also reported to predict a poor prognosis in patients with thyroid cancer." (PMID 37897503, 2023). "In addition, TTN mutations resulted in increased thyroid cancer sensitivity to eight drugs (P<0.05), especially the druggable genome." (PMID 35766333, 2022).
autoimmune disease (5 papers, 2011 to 2025). A disorder resulting from loss of function or tissue destruction of an organ or multiple organs, arising from humoral or cellular immune responses of the individual to their own tissue constituents. "Being an autoimmune disease, MG correlates with the presence of detectable antibodies directed against the acetylcholine receptor, muscle-specific kinase, lipoprotein-related protein 4, agrin, titin, and ryanodine in the postsynaptic membrane at the NMJ." (PMID 33767779, 2021).
diastolic heart failure (5 papers, 2015 to 2025). Heart failure caused by abnormal myocardial relaxation during diastole leading to defective cardiac filling. "Changes in this dynamic and reversible action can contribute to cardiac dysfunction, where, for example, hyperacetylation of titin was shown to promote cardiac stiffness and worsen cardiac relaxation in a rodent model of diastolic heart failure." (PMID 40915388, 2025). "Understanding and altering transcriptional regulation of titin represents a therapeutic target for treating systolic and diastolic heart failure." (PMID 32859027, 2020). "These analyses identified cardenolides as inhibitors of RBM20-mediated titin splicing, opening the possibility to treat diastolic heart failure by modulating titin splicing through drugs targeting RBM20." (PMID 32276354, 2020). "Based on our identification and characterization of cardenolides as inhibitors of titin splicing, we suggest them as promising leads to modulate titin’s elastic properties as a targeted approach to treating diastolic heart failure." (PMID 29889873, 2018). "The elastic scaffold protein titin is in addition to collagen the main determinant of cardiac filling in diastole and would therefore be a prime therapeutic target for diastolic heart failure." (PMID 29889873, 2018). "Many molecules and signaling pathways affect phosphorylation of these regions and further understanding of their control may provide an opportunity to selectively modify titin and improve both systolic and diastolic heart failure." (PMID 32859027, 2020). "Nevertheless, it failed to improve cardiac function in patients.Accordingly, we chose titin directed alternative splicing as our therapeutic target for diastolic heart failure and developed a cell based assay to identify small molecules that inhibit the recently identified titin splice factor RBM20." (PMID 29889873, 2018).
gastric adenocarcinoma (5 papers, 2021 to 2023). "Variants in specific genes, such as TTN, can influence cell proliferation that leads to cancer, in which studies that investigated the accumulation of mutations in several genes that lead to gastric adenocarcinoma showed TTN among the 10 most mutated genes." (PMID 37763132, 2023). "Some report that TTN was at the top ranking of mutated genes in multiple solid tumors, including the gastric adenocarcinoma, small cell lung cancer, and colorectal adenocarcinoma." (PMID 34368351, 2021). "There were also reports that TTN was at the top ranking of mutated genes in multiple solid tumors, including the gastric adenocarcinoma, small cell lung cancer and colorectal adenocarcinoma." (PMID 34046362, 2021). "TTN was also reported to be more expressed in gastric adenocarcinoma." (PMID 36982287, 2023).
hypothyroidism (5 papers, 2013 to 2025). Abnormally low levels of thyroid hormone. "Our findings particularly the observed association between dual AChR/Titin positivity, greater disease severity, and higher rates of thyroid dysfunction, primarily hypothyroidism." (PMID 41393996, 2025). "Long-term hypothyroidism (which results in diastolic dysfunction) changed the titin isoform ratios as well." (PMID 24367651, 2013). "A hypothyroidism rat model shows increased expression of a larger titin isoform." (PMID 24367651, 2013). "Moreover, the greater the diversity of autoantibodies present in MG patients (e.g., concurrent presence of AChR, Titin, and MuSK antibodies), the higher the incidence of thyroid dysfunction, among which Hashimoto’s thyroiditis is the most common and often progresses to hypothyroidism." (PMID 41393996, 2025).
myocardial ischemia (5 papers, 2012 to 2025). A disorder of cardiac function caused by insufficient blood flow to the muscle tissue of the heart. "Further comprehensive experiments will be needed to better examine the role of this TTN missense variant in the pathogenesis of ischemia-associated VF, utilizing a novel human in vitro model of acute myocardial ischemia constructed by patient-derived iPSCs." (PMID 41552678, 2025). "In contrast, a previous study demonstrated that the metalloproteinase-2 (MMP-2) matrix degrades titin after 10 min of reperfusion in a rat myocardial ischemia/reperfusion injury model." (PMID 38203744, 2024). "Among them, four glycolytic enzymes, L-LDH, GAPDH, GPI, PGAM2, and two targets of MMP, gelsolin and isoform 8 of titin, are significantly released into the effluent during myocardial ischemia." (PMID 22443514, 2012). "Schulz and colleagues showed that MMP-2 is activated and thereby degrades myocardial contractile proteins such as myosin light chain, titin and troponins, as well as sarcoplasmic/ endoplasmic reticulum Ca2+ ATPase 2a (SERCA2a) and junctophilin-2 during myocardial ischemia/reperfusion injury." (PMID 32977437, 2020).
Stroke (5 papers, 2021 to 2025). Sudden impairment of blood flow to a part of the brain due to occlusion or rupture of an artery to the brain. "However, the role of titin in passive tension may vary considerably in different muscles, and whether titin isoform size was altered in stroke patients with hypertonia was still controversial." (PMID 37332999, 2023).